H1-2 (H1.2 linker histone, cluster member)
Description:
Histone H1 protein binds to linker DNA between nucleosomes forming the macromolecular structure known as the chromatin fiber. Histone H1-2 is required for the condensation of nucleosome chains into higher-order structured fibers. Compared to other histone H1 variants, H1-2 plays an essential role in nucleosome condensation: its absence leads to global chromatin decompaction, which is not observed when depleting other histone H1 variants. Histone H1-2 also acts as a histone reader: specifically recognizes and binds histone H3 trimethylated at 'lys-27' (H3K27me3). Histones H1 also promote formation of the H3K27me3 mark by the PRC2/EED-EZH2 complex, possibly by facilitating restoration of H3K27me3 post-replication. Together with histone H1-3, histone H1-2 acts as a regulator of splicing, most specifically exon skipping and intron retention events: histone H1-2 has a high affinity for exons and regulates splicing by affecting RNA polymerase II (RNAPII) elongation. Also acts as a regulator of individual gene transcription through chromatin remodeling, nucleosome spacing and DNA methylation.
Synonyms: H1F2; HIST1H1C; H1.2; H1s-1; H1c
Tractability: PROTAC: ubiquitination databases record sites on it.
Gene: Protein-coding gene on chromosome 6 (26,054,760 to 26,056,470, reverse strand). Ensembl gene ENSG00000187837.
Subcellular location: Nucleus; Nucleus, nucleolus; Chromosome
Subcellular location (Human Protein Atlas): Nucleoli rim; Nucleoplasm
Pathways (Reactome):
Cellular responses to stimuli: Formation of Senescence-Associated Heterochromatin Foci (SAHF)
Programmed Cell Death: Apoptosis induced DNA fragmentation
Gene Ontology:
Molecular function: chromatin DNA binding; histone H3K27me3 reader activity; protein binding; RNA binding; structural constituent of chromatin; double-stranded DNA binding; nucleosomal DNA binding; DNA binding
Biological process: chromosome condensation; facultative heterochromatin formation; regulation of mRNA splicing, via spliceosome; negative regulation of DNA recombination; nucleosome assembly
Cellular component: chromosome; euchromatin; heterochromatin; nucleolus; nucleoplasm; nucleus; chromatin; nucleosome
Genetic constraint (gnomAD): Loss-of-function variants: 7 observed, 7.16 expected, observed/expected ratio (o/e) 0.98, 90% interval 0.55 to 1.73. That is too few expected variants to judge how well the gene tolerates losing a copy. Missense variants: 703 observed, 292.74 expected, observed/expected ratio (o/e) 2.4. Synonymous variants: 300 observed, 126.03 expected, observed/expected ratio (o/e) 2.38.
Homologues: Orthologues: chimpanzee H1-2 (99% identical), dog H1-2 (92% identical), guinea pig H1-2 (92% identical), mouse H1f2 (88% identical), rat H1f2 (88% identical), macaque H1-2 (88% identical), Caenorhabditis elegans hil-3 (27% identical), Caenorhabditis elegans hil-4 (25% identical), Caenorhabditis elegans hil-6 (24% identical), Caenorhabditis elegans hil-2 (23% identical), Caenorhabditis elegans hil-5 (23% identical). Paralogues in human: H1-4 (87% identical), H1-3 (83% identical), H1-5 (81% identical), H1-1 (67% identical), H1-6 (51% identical), H1-0 (40% identical), H1-8 (34% identical), H1-10 (30% identical), H1-7 (24% identical).
Diseases named in the same sentence as H1-2 in open-access papers:
H1-2 is named in the same sentence as 43 diseases in open-access papers, as found by Europe PMC text mining. Sharing a sentence is not in itself a finding about the gene and the disease. The quoted sentences say what the papers report.
Pancreatic Cancer (2 papers, 2020). "Ectopic AGR2 expression partially negated the H-1-2 inhibitory effect on invasion and migration of pancreatic cells and on xenograft pancreatic tumors growth, and it also compromised the H-1-2 promotional effect on survival of mice." (PMID 32322663, 2020).
tumor (4 papers, 2020 to 2025). "H1-2 acts as a signaling molecule to initiate apoptosis, and its deletion may lead to resistance to apoptosis in mice and tumor cells." (PMID 36685937, 2022).
H1-2 also shares sentences with these, for which no sentence is quoted: cancer (11 papers); breast cancer (5); diabetic retinopathy (3); infection (3); neuroblastoma (3); adrenocortical carcinoma (2); cervical cancer (2); lung carcinoma (2); meningioma (2); pituitary adenomas (2); viral infection (2); adenoma (1); allergic rhinitis (1); amyotrophic lateral sclerosis (1); asthma (1); astrocytoma (1); atherosclerosis (1); bladder cancer (1); brain disease (1); COVID-19 (1); E. coli infection (1); endometriosis (1); follicular lymphoma (1); hemochromatosis (1); hepatocellular carcinoma (1); infertile (1); influenza (1); malaria (1); melanoma (1); metastatic tumors (1).
A further 11 diseases each share a sentence with H1-2 in 1 paper.